ANKRD39 (ankyrin repeat domain 39)
Synonyms: MGC41816
Tractability: PROTAC: ubiquitination databases record sites on it.
Gene: Protein-coding gene on chromosome 2 (96,836,611 to 96,858,016, reverse strand). Ensembl gene ENSG00000213337.
Subcellular location (Human Protein Atlas): Nucleoplasm; Vesicles
Genetic constraint (gnomAD): Loss-of-function variants: 18 observed, 19.4 expected, observed/expected ratio (o/e) 0.93, 90% interval 0.64 to 1.38. The upper end of that interval is the gene's LOEUF score, 1.38, which puts it in group 5 of 6, group 1 being the genes least tolerant of losing a copy. Missense variants: 243 observed, 237.04 expected, observed/expected ratio (o/e) 1.03, 90% interval 0.92 to 1.14. Synonymous variants: 106 observed, 109.87 expected, observed/expected ratio (o/e) 0.96, 90% interval 0.82 to 1.13.
Homologues: Orthologues: chimpanzee ANKRD39 (100% identical), macaque ANKRD39 (98% identical), mouse Ankrd39 (90% identical), rabbit ANKRD39 (90% identical), guinea pig ANKRD39 (89% identical), pig ANKRD39 (89% identical), rat Ankrd39 (72% identical), zebrafish ankrd39 (51% identical), tropical clawed frog ankrd39 (51% identical), Drosophila melanogaster CG44001 (41% identical). Paralogues in human: CDKN2C (25% identical), CDKN2D (24% identical).
Diseases named in the same sentence as ANKRD39 in open-access papers:
ANKRD39 is named in the same sentence as 5 diseases in open-access papers, as found by Europe PMC text mining. Sharing a sentence is not in itself a finding about the gene and the disease.
ANKRD39 shares sentences with these, for which no sentence is quoted: breast carcinoma (1 paper); colorectal cancer (1); lung carcinoma (1); ovarian carcinoma (1); prostate carcinoma (1).